INS (insulin)
Diseases named in the same sentence as INS in open-access papers (continued):
Sharing a sentence is not in itself a finding about the gene and the disease.
Obesity (continued). "Thus, the manipulation of redox status and its effects on the modulation of signalling pathway components might promote insulin signalling but may also contribute to obesity." (PMID 33893069, 2021). "Moreover, those with obesity-induced IR and hyperglycemia could gain some benefits from calcitriol via its ability to enhance healthy pancreatic beta cells to secrete insulin, and protect these cells from hyperglycemic effects." (PMID 34836382, 2021). "In this meta-analysis, the finding of temporal sequencing (in which changes in fasting insulin level precede changes in weight) is not consistent with the assertion that obesity causes noncommunicable chronic diseases and premature death by increasing levels of fasting insulin." (PMID 33710289, 2021). "In a knock-out mouse model of SRA1 has displayed improved insulin sensitivity and resistance to developing obesity under high-fat diet conditions, but obesity and T2D themselves might have a non-significant influence on SRA1 expression levels, reflecting a plausible absence of reverse causation." (PMID 34685582, 2021). "Indeed, DNA methylation plays an important role in adipogenesis, and adipose tissue expansion, and changes in DNA methylation patterns of SM in specific genes may affect to whole-body insulin sensitivity in obesity." (PMID 33803198, 2021). "Interestingly, non-insulin-resistant children with overweight or obesity that became insulin-resistant during puberty showed a significant decrease in the concentration of 25(OH)D over time and HDL-c while they showed a significant increase in WC and TAG levels." (PMID 34960039, 2021). "Thus, Ex-4 improves insulin sensitivity in neurons under obesity-induced hyperlipidemia conditions." (PMID 33435277, 2021). "According to the carbohydrate-insulin model of obesity, the way we metabolize processed carbohydrates and foods that are higher on the glycemic index (such as starchy, refined, and sugary foods) promotes fat storage in fat cells and is driven by spikes in insulin levels." (PMID 34899613, 2021). "Attempts to differentiate healthy and unhealthy normal weight and obesity have focussed on body fat distribution and ectopic fat deposition but have highlighted that poor metabolic health, regardless of weight, is characterized by higher liver fat, higher visceral fat and insulin resistance." (PMID 34309471, 2021). "Obesity-mediated inflammation and lipotoxicity through ectopic lipid deposition contribute to vascular remodeling in ectopic organs (e.g., liver, muscle, pancreas, heart) as well as in tumor tissues, promoting insulin resistance, cardiovascular diseases and tumor progression." (PMID 34660572, 2021). "Moreover, different authors have investigated BBR action on gut microbiota: BBR treatment modifies gut composition in animal models of obesity, alleviating the inflammation state induced by LPS overproduction and improving energy metabolism and insulin resistance condition." (PMID 34360538, 2021). "Therefore, VS extract effectively diminished obesity and hyperglycemia by suppressing C/EBPα-mediated lipogenesis in the AT and liver, enhancing PPARα-mediated fatty acid β-oxidation in muscle, and PPARγ-mediated insulin sensitivity in AT and muscle." (PMID 33671428, 2021). "However, the observed anabolic and mitogenic effects of insulin on adrenal cortex from preclinical models led to the hypothesis of the potential existence of bilateral relationship between obesity and AIs." (PMID 32736549, 2020). "Yet, insulin may not be the primary cause for reduced hepatic autophagy in obesity and other possible mechanisms might coexist." (PMID 32015340, 2020). "The vagal ability to modulate insulin secretion has been confirmed, and there is consensus in considering vagal innervation as the part of the nervous system that stimulates ‘rest and digest’ and ‘feed and breed’ processes and is considered to be involved in the development of diet‐induced obesity." (PMID 32232927, 2020).
Obesity (continued). "In addition to soluble factors, direct cell-cell contact between islet macrophages and β-cells, possibly through nanotubes, seems to be an important mechanism as well, by which macrophages can decrease β-cell insulin secretion and which is increased in obesity." (PMID 32709161, 2020). "It is tempting to speculate that the contrasting changes in adipocyte mitochondrial respiration rates in states of varied insulin, with corresponding varied ketones, further contribute to adipocyte energy use and size and, by extension, obesity progression or regression." (PMID 32872407, 2020). "Additionally, it has been shown that infections of mice with different species of parasitic helminths are associated with significant increases in ILC2s, eosinophils, M2 MACs, and Th2 cytokines that result in restoration of glucose levels and improved insulin sensitivity in mouse models of obesity." (PMID 33613446, 2020). "The risk factors, genetic and environmental including obesity, sedentary lifestyle, smoking, alcohol consumption, and diet have been considered to be a major reason of the alarming rise in T2DM worldwide and are the focus of therapeutic targeting to alleviate impaired insulin secretion and IR." (PMID 32998300, 2020). "Therefore, pharmacological approaches to alter satiation and insulin secretion may have an impact on metabolic disorders such as obesity." (PMID 32272767, 2020). "Moreover, humans with T1D now increasingly exhibit obesity and impaired insulin sensitivity." (PMID 33105667, 2020). "Interestingly, insulin-induced RXRα S22 phosphorylation is dampened by diet-induced obesity." (PMID 32249683, 2020). "Therefore, androgen receptors in adipocytes may influence adipokine levels, and they may control insulin sensitivity and glucose tolerance independently of obesity." (PMID 33488512, 2020). "Notably, the beneficial effects of chrysophanol on reducing FBG, GGT, and ITT were largely diminished in SIRT6 FKO obese mice, suggesting a critical role of SIRT6 in mediating the effects of chrysophanol in preventing obesity, improving glucose tolerance and insulin sensitivity." (PMID 33274005, 2020). "Obesity can lead to metabolic disturbances, such as higher levels of pro inflammatory cytokines (e.g. tumour necrosis factor-α and interleukin-6), adipokines (e.g. glucose, insulin, and leptin), and endogenous sex steroids, which may increase cancer risk." (PMID 33079929, 2020). "This study aimed to investigate the linkage between serum markers of obesity and risk of cardiovascular diseases, with particular reference to the adipokines galectin-3, plasminogen activator inhibitor-1 (PAI-1), IL-1β, CRP, monocyte chemoattractant protein-1 (MCP-1), and insulin." (PMID 32290863, 2020). "Therefore, Rg3 enhances insulin activity in obesity and T2D models." (PMID 32161549, 2020). "Consequently, mildly elevated serum bilirubin might improve obesity-related dysglycemia by partially enhancing insulin sensitivity." (PMID 32802055, 2020). "The study of diet-induced obesity and models of prenatal undernutrition and overnutrition has revealed several common mechanisms that contribute to the understanding of the physiological basis of reduced insulin sensitivity and provide some new insights into T2DM etiology in humans." (PMID 32530969, 2020). "An increase in leptin and insulin levels has been blamed to explain the decrease in ghrelin levels in individuals with obesity; it has also been suggested that this alteration could represent a physiological adaptation of the body to obesity once a positive energy balance is reached." (PMID 32442310, 2020). "Notably, genetic ablation of GDF15 in a mouse model of skeletal muscle‐specific deficiency of Crif1, an integral protein of the large mitoribosomal subunit, prevented a mitochondrial stress‐driven improved insulin sensitivity and resistance to diet‐induced obesity." (PMID 32026535, 2020). "Moreover, glucose and insulin levels were also elevated in obesity." (PMID 33329380, 2020).
Obesity (continued). "Our findings indicate that the chronic upregulation of insulin signaling through the peripheral IR during diet-induced obesity contributes to the development of hepatic dysfunction, and that targeting the IR in peripheral tissues may be an effective approach to treat NAFLD." (PMID 32350271, 2020). "In conclusion, the present in vitro system provides insight into the molecular and metabolic changes of mature adipocytes under conditions of high glucose and insulin, which may help to understand the process of in vivo adipocyte hypertrophy during the development of obesity." (PMID 32618419, 2020). "Interestingly, in subjects with obesity, both muscle myostatin expression and circulating follistatin levels decreased after weight loss due to bariatric surgery, in parallel with the decrease in LBM and the increase in insulin sensitivity." (PMID 32316563, 2020). "The concept that SST might involve in obesity emerged from the regulation of insulin release." (PMID 32272767, 2020). "Obesity correlates with cardiovascular risk, since it is associated with increased fasting plasma triglycerides and low density lipoprotein (LDL) cholesterol, low levels of high density lipoprotein (HDL) cholesterol, elevated blood glucose and insulin levels, and high blood pressure." (PMID 33114564, 2020). "Interestingly, microbiota dysbiosis in obesity could enhance the acetate levels, promoting glucose-stimulated insulin secretion, increased ghrelin secretion, further increasing obesity." (PMID 33255588, 2020). "Thus, exercise prevents and controls HFD-induced obesity and may modulate chromium distribution in insulin target tissues." (PMID 32260278, 2020). "Insulin and IGF-1 are of particular oncological interest, since both are known as growth factors for tumor cells and might provide a mechanistic link between the increased risk of obesity and breast cancer incidence and recurrence." (PMID 32819413, 2020). "Therefore, we conclude that WWP1 may be involved in maintaining WAT function, including the response to oxidative stress, mitochondrial function, and insulin signaling in obesity." (PMID 31965758, 2020). "However, it remains unclear whether the TyG index, as predictor for the incidence of prediabetes, is superior to other indices, including obesity, abnormal lipid profiles and other non-insulin-based IR indices." (PMID 33059672, 2020). "Therefore, proper control of insulin level and insulin signalling could be beneficial to maintain the balance between the differentiation and dedifferentiation of adipocytes to prevent obesity and its related disorders." (PMID 31989870, 2020). "Moreover, correlation analysis demonstrated that lncRNA RP11-20G13.3 in adipose tissue from obese and non-obese children was positively associated with obesity indices, circulating levels of insulin, LDL-C,and hs-CRP." (PMID 32368256, 2020). "Therefore, we have developed the Low-Insulin-Method and integrated it into the multi-component, occupational healthcare program SHAPE-AND-MOTION-Medical-Accompanied-Slimming (SAMMAS) to reduce daily insulin levels for long-term weight reduction in overweight or obesity." (PMID 33007918, 2020). "The mechanisms by which obesity affects the incidence and survival of kidney cancer might include insulin/insulin-like growth factor signals, chronic inflammation, sex steroids, as well as the treatment disparities between obese patients and normal-weight patients." (PMID 33005476, 2020). "The chronic low-grade inflammation associated with obesity also contributes to excessive release of lipids by adipocytes, as the inflammatory cytokine TNFα can also induce lipolysis in a manner independent of insulin signalling." (PMID 33292104, 2020). "Similarly, SORCS2 methylation, which functions to regulate fasting insulin levels and secretion of insulin, was potentially associated with increased obesity at 36 months but was not statistically significant in this relatively small sample." (PMID 32059710, 2020).
Obesity (continued). "In addition, upon HFD treatment, it was observed that there was an increase in fatty acid oxidation (elevated oxygen consumption, metabolic rate, and total energy expenditure), improved glucose tolerance and insulin sensitivity, as well as an attenuation of obesity and hepatic steatosis." (PMID 32174890, 2020). "Moreover, weight loss in individuals with obesity after a low-energy liquid diet was associated with improvements in insulin sensitivity but IGF-1 was not significantly modified." (PMID 32806629, 2020). "The association of leptin with amylin, a peptide hormone released with insulin by pancreatic beta cells which modulate glucose and energy homeostasis, showed enthusiastic results, predominantly mediated by decreased feeding and increased central leptin sensitivity in diet-induced obesity." (PMID 33192583, 2020). "Physiological parameters, lipid droplet accumulation, inflammatory biomarkers, antioxidant biomarkers, mitochondrial biogenesis, insulin sensitivity, and hepatic fibrosis were determined to examine whether PSO intervention prevents obesity-associated metabolic syndrome." (PMID 32751794, 2020). "Thus, the author suggested that the treatment with MaR1 might be a useful therapy to improve insulin sensitivity in murine models of obesity." (PMID 32377160, 2020). "Adipokine production from the adipose tissue may be influenced by the nutritional status of the animal, in particular considering that obesity disrupts the balance of adipokine secretion, which is prejudicial to insulin action in peripheral tissues, such as muscle or liver." (PMID 32966299, 2020). "However, insulin is related to increased bodyweight and obesity." (PMID 32684824, 2020). "However, chronic metabolic disturbances such as those seen in obesity might lead to sustained over‐activation of Notch signaling activity in ECs and this subsequently would contribute to impaired insulin sensitivity." (PMID 32187826, 2020). "Additionally, HDAC5 can interact with the GLUT4 enhancer factor (GEF) in adipocytes for the repression of Glut4 promoter activity, suggesting a plausible mechanism by which Glut4 expression and insulin-mediated glucose uptake are dysregulated in obesity and T2D." (PMID 33193730, 2020). "Complications of pregnancy were more frequent for women with obesity compared to normal weight women with significantly more gestational hypertensive disorders (gestational hypertension and preeclampsia) and gestational diabetes (requiring insulin or simple diet)." (PMID 33243175, 2020). "Finally, due to the relevance of the stimulation of taste receptors at the GI level, specifically designed functional foods incorporating MB extracts (or isolated miraculin) represent an innovative potential strategy for the control of food intake to help prevent obesity and insulin resistance." (PMID 33333960, 2020). "In addition, animals without the TNF receptor had restored insulin sensitivity, strongly supporting the role of inflammation in obesity and its associated metabolic disorders." (PMID 32183037, 2020). "Vaspin, a visceral adipose tissue-derived serine protease inhibitor with insulin-sensitizing effects, which belongs to the serpin superfamily, was another regulatory molecule analyzed in this study that plays an important role in maintaining metabolic homeostasis in obesity state." (PMID 32917052, 2020). "Additionally, this altered brain insulin action may be a key pathological factor in regulating glycemic control in individuals with obesity, T2D, aging, and Alzheimer's disease." (PMID 32849302, 2020). "Finally, higher levels of insulin (p = 0.039) and leptin (p = 0.082) were detected in the blood of GF mice receiving feces from aged versus adult mice, which is consistent with the changes seen in obesity." (PMID 33046129, 2020).
Obesity (continued). "This study demonstrates that TMBIM6−/− mice develop obesity and hepatic steatosis not by a decreased energy expenditure or altered muscle and liver insulin resistance but rather by increased insulin-dependent fat storage caused by changes in glucose-mediated Ca2+ oscillations in pancreatic β cells." (PMID 32394396, 2020). "Insulin is the principal anabolic hormone responsible for tissue uptake and storage of energy rich nutrients following ingestion of a meal, and previous studies have documented a positive relationship between obesity status and elevated insulin concentrations in animal models and humans." (PMID 31238601, 2019). "In climacteric women, with increased risk for obesity, MS becomes more prevalent, increasing the incidence of cardiovascular disease and the risk of acute myocardial infarction (AMI), a vulnerability attributed to the decrease of oestrogen and insulin resistance." (PMID 31830047, 2019). "Whether the GM profile is causally related to the host pLPHC diet phenotype, which included obesity-protection despite increased total energy intake due to increased adaptive thermogenesis and increased glucose tolerance and whole-body insulin sensitivity, is currently unclear." (PMID 31019501, 2019). "Strengths of this study include its study design which raises interesting questions regarding the interplay of leptin, insulin and C-peptide during the neonatal period and how it would influence the programming of obesity during infancy, childhood and may be adulthood." (PMID 31975995, 2019). "Therefore, this suggests that the simultaneously elevated plasma levels of these crucial markers may induce significant pathophysiological changes in the adipose tissue compartment in obesity, including changes in insulin sensitivity and lipid metabolism." (PMID 31443599, 2019). "However, in the obesity spectrum, there are individuals able to expand their subcutaneous adipose tissue without increasing the visceral fat content, which leads to preserved insulin sensitivity and the MHO phenotype." (PMID 31920976, 2019). "Obesity is associated with whole-body insulin resistance yet this resistance may differ between insulin responsive tissues and not always be directly related to the degree of obesity." (PMID 30637483, 2019). "Importantly, the effects of recurrent obesity on serum corticosterone, glucose, and insulin were reversed by daisaikoto, indicating that this medicine may prevent weight regain by lowering serum corticosterone." (PMID 31920693, 2019). "However, further work is required to determine whether endogenous glucose production in the obese dams of this study whose obesity preexisted prepregnancy, is also reduced and importantly, rescued by exercise‐induced changes in hepatic insulin sensitivity." (PMID 31466137, 2019). "Our findings indicate that the components of the MRS reflect diverse biological factors related to weight gain, possibly including anabolic effects of preserved insulin sensitivity and protection from T2D, which are unlikely to be captured by single metabolites or other obesity-associated factors." (PMID 31560688, 2019). "Berry fruits have been recognized as capable of counteracting obesity and obesity-related metabolic disorders, through the inhibition of adipocyte differentiation, a decrease in lipogenesis, an increase in lipolysis, or mitigation of inflammatory and insulin resistance status." (PMID 31398785, 2019). "Therefore, reducing CerS6 could inhibit obesity induced CerS6 overexpression, leading to improved insulin sensitivity and reductions in metabolic disorders." (PMID 31067249, 2019). "Although starvation and obesity could not, on the surface, be more different, starvation is actually a key physiologic feature of both insulin and leptin deficiencies." (PMID 30357355, 2019). "Moreover, a state of unbalanced or increased amino acids associated with obesity, such as BCAA in the blood, may exacerbate obesity and insulin sensitivity." (PMID 31387549, 2019).